PRMT5 (protein arginine methyltransferase 5)
Diseases named in the same sentence as PRMT5 in open-access papers (continued):
Sharing a sentence is not in itself a finding about the gene and the disease.
breast carcinoma (continued). "We also show a novel link between the PRMT5-FUS-Pol II axis and intron retention within genes enriched for cell cycle progression in ER+/RB-deficient breast cancer cells." (PMID 37502925, 2023). "Arguably, the most research into how PRMT5 modulates cancer progression has been achieved in breast cancer research." (PMID 38132437, 2023). "Here, using two independent cohorts of breast cancer patients, we identified nuclear PRMT5 expression as an independent predictive marker of sensitivity to tamoxifen." (PMID 37458145, 2023). "In contrast, TNF receptor-associated factor 6 (TRAF6), another E3 ubiquitin ligase, promotes K63-linked polyubiquitination of PRMT5, enhancing its methyltransferase activity on histone H4R3 and breast cancer cell proliferation." (PMID 37928266, 2023). "Ms4322 is a PROTAC drug based on VHL, which can highly selectively reduce PRMT5 in breast cancer, cervical cancer, lung cancer, leukemia cells, and ER+ breast cancer cells and inhibit the growth of cancer cells." (PMID 36770884, 2023). "In breast cancer stem cells, it was shown that PRMT5 functions to methylate H3R2, allowing SET1 binding and H3K4 trimethylation at the FOXP1 promoter to activate FOXP1 transcription both in vitro and in vivo." (PMID 37795443, 2023). "PRMT5 regulates breast cancer cell growth through epigenetic silencing of DKK1 and DKK3, which are WNT/β-CATENIN pathway antagonists, thus resulting in up-regulation of WNT/β-CATENIN proliferative signaling." (PMID 37924099, 2023). "In summary, our study identifies nuclear PRMT5 as a novel regulator of ERα involved in Tam sensitivity in ERα+ breast cancers." (PMID 37458145, 2023). "This study is aimed to investigate and elucidate the exosomal circRHOT1/miR-204-5p/PRMT5 axis in breast cancer." (PMID 37924099, 2023). "In MCF7 breast cancer cells, we validated transcript reductions in select correlated genes by qRT-PCR following transient knockdown of PRMT5 by shRNA, demonstrating a functional significance of the positive correlation." (PMID 37861290, 2023). "Lastly, we found that, compared to the single agent, co-treatment of TRAF6 and PRMT5 inhibitors significantly decreased cell viability in breast cancer cells, which is in part achieved by enhancing cell apoptosis." (PMID 37173967, 2023). "In conclusion, our findings reveal that exosomal circRHOT1 plays crucial roles in the progression of breast cancer through the miR-204-5p/PRMT5 axis." (PMID 37924099, 2023). "Our previous study demonstrated that depletion of PRMT5 significantly suppressed breast cancer cell proliferation and tumor growth." (PMID 37173967, 2023). "Our work identifies new and potentially clinically actionable sensitivities in ovarian and breast cancers through combination of PRMT5 inhibitors with clinically approved drugs and as a single agent in PARP inhibitor–resistant cancers." (PMID 37861290, 2023). "The current study strengthens the role of circRHOT1, miR-204-5p, and PRMT5 in breast cancer development and provides a potential treatment strategy for breast cancer." (PMID 37924099, 2023). "PRMT5 is overexpressed in many malignant tumours, including breast cancer, and plays a role in the development of cancer." (PMID 37237082, 2023). "findings show that PRMT5 promotes aerobic glycolysis of breast cancer cells by regulating the liver X receptor α (LXRα)/NF‐κBp65 pathway." (PMID 36999124, 2023). "To investigate the biological function of TRAF6-mediated PRMT5 ubiquitination, we reintroduced PRMT5-WT, PRMT5-3A, or PRMT5-6KR into PRMT5-depleted breast cancer cells." (PMID 37173967, 2023). "The analyses of PRMT5 expression in two large cohorts of luminal breast cancer samples and functional studies revealed a key role of PRMT5 expression in the nucleus of tumor cells in premenopausal women treated with tamoxifen." (PMID 37458145, 2023).
breast carcinoma (continued). "Using a genome-wide CRISPR screen, we identified protein arginine methyltransferase 5 (PRMT5) as a molecular vulnerability in ER+/RB1-knockout (RBKO) breast cancer cells." (PMID 37502925, 2023). "PRMT5 is overexpressed or hyperactive in a number of tumor types and promotes tumor progression, including breast cancer, acute myeloid leukemia, lung, ovarian, glioblastoma, and prostate cancer." (PMID 35563196, 2022). "Taking into account both PRMT5 and MEP50 mRNA levels helps to better stratify patients associated with poor prognosis in these two breast cancer subgroups." (PMID 36230689, 2022). "Here we found that the transcription factor Slug associates with PRMT5 and LSD1 in a complex and facilitates the breast cancer invasion in vitro." (PMID 35655230, 2022). "Protein arginine methyltransferase 5 (PRMT5) is highly expressed in breast cancer and represents a potential druggable target for breast cancer treatment." (PMID 35563196, 2022). "In this study, we examined the expression level of MEP50 and PRMT5 mRNA and their association with recurrence-free survival (RFS) in the different breast cancer subgroups and various TNBC subtypes." (PMID 36230689, 2022). "We found that breast cancer samples expressed significantly higher PRMT5 or LSD1 levels than normal breast cells, (n = 1222, P < 0.01)." (PMID 35655230, 2022). "GSK3326595 is also a selective PRMT5 inhibitor that inhibits the activation of Akt to sensitive breast cancer cells to etoposide and cisplatin." (PMID 35216622, 2022). "Since compounds A, B, and C have inhibitory effects on PRMT5, we analyzed the effects of the three compounds on the proliferation of breast cancer cells in comparison with that of tadalafil." (PMID 35563196, 2022). "It has been reported that TRAF4 can enhance the nuclear protein level of PRMT5 in breast cancer cells, thereby promoting the proliferation of breast cancer cells." (PMID 35692762, 2022). "The arginine methyltransferase PRMT5 is an emerging therapeutic target for various cancers including breast cancer." (PMID 36230689, 2022). "The dimethylation of Akt at R391 by PRMT5 is essential for its kinase activity and breast cancer tumorigenesis." (PMID 35216622, 2022). "Normal breast tissues express higher MEP50 (in this study) and PRMT5 compared to breast cancer at the plasma membrane." (PMID 36230689, 2022). "We demonstrated that PRMT5 and LSD1 cooperate to promote the EMT and invasion of cancer cells, and that PRMT5 expression is positively correlated with LSD1 expression in breast carcinoma specimens." (PMID 35655230, 2022). "As a type 2 PRMTs, PRMT5 has been found highly expressed and often correlated with poor prognosis in multiple cancers, including lung cancer, hepatocellular carcinoma, and breast cancer." (PMID 36474242, 2022). "For this purpose, we analyzed the prognostic value of PRMT5 or MEP50 mRNA in the two subpopulations expressing high (> median) or low (< median) MEP50 or PRMT5 mRNA levels in the different breast cancer subgroups." (PMID 36230689, 2022). "We have previously shown that TNBC express low levels of nuclear PRMT5 compared to the other breast cancer subgroups and to normal tissues, suggesting a lower nuclear PRMT5 activity in TNBC." (PMID 36230689, 2022). "Altogether, our study reports the expression of the PRMT5 cofactor (MEP50) and substrate (H4R3me2s) in breast cancer and highlights the association of PRMT5 and MEP50 mRNA with prognosis in luminal B and TNBC breast cancer subgroups and certain TNBC subtypes." (PMID 36230689, 2022). "Several studies have reported that the inhibition of PRMT5 in breast cancer can promote a decrease in metastatic capacity and proliferation." (PMID 35743249, 2022). "Our team previously found that the FDA-approved drug tadalafil can act as a PRMT5 inhibitor and enhance the sensitivity of breast cancer patients to doxorubicin treatment." (PMID 35563196, 2022).
breast carcinoma (continued). "Previous results from our group showed that PRMT5 inhibition in breast cancer cells can promote the m6A modification of BRCA1 mRNA and reduce its stability." (PMID 35563196, 2022). "PRMT5 inhibition also altered the growth characteristics of breast cancer cells and induced their death." (PMID 33462997, 2021). "Collectively, these results show that PRMT5 controls breast cancer cell growth through epigenetic silencing of WNT/β‐CATENIN pathway antagonists, DKK1 and DKK3, resulting in up‐regulation of WNT/β‐CATENIN proliferative signalling." (PMID 33462997, 2021). "Lastly, we found that the expression levels of PRMT5 is positively correlated with AKT1-R391-me2s signal in breast cancer patient specimens." (PMID 34103528, 2021). "To assess if PRMT5 inhibition can impact invasiveness of breast cancer cell lines, we utilized Boyden invasion assay." (PMID 33462997, 2021). "Our findings show that PRMT5 levels are up‐regulated in breast cancer cell lines, and that PRMT5 is involved in epigenetic silencing of a different set of WNT antagonists compared with lymphoma cells." (PMID 33462997, 2021). "In the current study, we show that PRMT5 levels are up‐regulated in different types of breast cancer cell lines compared with normal human mammary epithelial cells." (PMID 33462997, 2021). "Enhanced PRMT5 expression has also been shown in breast cancer cell lines as well as clinical samples of ductal carcinoma." (PMID 33462997, 2021). "Several studies have demonstrated high expression of PRMT5 in various tumor types including lung cancer, breast cancer, hematologic malignancies, glioblastoma, and colorectal cancer, and these studies demonstrate an important role for PRMT5 in tumorigenesis." (PMID 35111150, 2021). "The allosteric regulation between PRMT7 and PRMT5 should be considered, especially in breast cancer, where the role of PRMT5 in cancer-initiating cells and disease progression has been well established." (PMID 34440512, 2021). "In accord with this result, Western blot analysis showed that PRMT5 protein expression was increased in breast cancer cell lines compared to normal HMECs." (PMID 33462997, 2021). "For instance, PRMT5 aids cellular proliferation, migration, and invasion in breast cancer cells by inhibiting the expression of Dickkopf WNT signaling pathway inhibitor 1 (DKK1) and DKK3, known antagonists of the wnt/β-catenin pathway." (PMID 34685445, 2021). "More recently, PRMT5 expression was shown to be increased in breast cancer stem cells (BCSCs), and that its knock down reduces proliferation and self‐renewal of BCSCs both in vitro and in vivo." (PMID 33462997, 2021). "In our study, we found that PRMT5 inhibition reduces viability of breast cancer cells and induces their death." (PMID 33462997, 2021). "A study shows that FOXP1 is a key factor in PRMT5-induced breast cancer stem cells and PRMT5 can be recruited to the FOXP1 promoter to facilitates recruitment of H3R2me2s, SET1 and H3K4me3." (PMID 32859239, 2020). "PRMT5 is overexpressed in chronic myeloid leukemia stem cells and breast cancer stem cells, and is required for CSC proliferation and self-renewal." (PMID 32859041, 2020). "We previously demonstrated that PRMT5 inhibition by DS-437 enhances anti-tumor effects of anti-erbB2/neu monoclonal antibody targeted therapy in a drug-resistant syngeneic murine breast cancer model by inhibiting Treg function and induction of tumor immunity." (PMID 32328070, 2020). "PRMT5 is the most promising target for the treatment of breast cancer based on the principle of histone methylation." (PMID 33193750, 2020). "This is exemplified by the activation of FOXP1 transcription in breast cancer stem cells and DVL3 transcription, an activator of Wnt/β-catenin, in CML-LSCs (leukemic stem cells), which were linked with PRMT5 activity." (PMID 32743345, 2020).
breast carcinoma (continued). "PRMT5 epigenetically upregulates Forkhead box protein P1 (FOXP1) expression through histone H3 methylation (H3R2me2s) at this gene promotor for breast cancer stem cells’ maintenance." (PMID 32859041, 2020). "PRMT5 is known to be expressed universally but is overexpressed in a large number of cancers, including breast cancer." (PMID 30800128, 2019). "Next, we examined the effect of PRMT5 inhibition on breast cancer cell cycle progression using flow cytometry." (PMID 30957988, 2019). "Healthy breast tissues display significantly high levels of PRMT5 at the cell plasma membrane compared to cancerous tissues from all breast cancer subtypes." (PMID 30957988, 2019). "Here, we examine the expression of PRMT5 in a human breast cancer cohort obtained from the Institut Curie, and evaluate the therapeutic potential of pharmacological inhibition of PRMT5 in TNBC." (PMID 30957988, 2019). "We observe that, as for mRNA, PRMT5 protein is expressed at similar levels in the different breast cancer subtypes and in healthy breast tissues." (PMID 30957988, 2019). "We further show here that PRMT5 is differentially localized in breast cancers and healthy mammary tissue, and that some important subcellular localization differences can be noted between breast cancer subtypes." (PMID 30957988, 2019). "Here we describe our recent findings that PRMT5 is a critical regulator of breast cancer stem cell survival via the epigenetic regulation of FOXP1." (PMID 29876520, 2018). "Cell cycle analysis revealed that in a subset of lymphoma and breast cancer cell lines, PRMT5 inhibition triggers G1 cell cycle arrest and subsequent induction of the sub-G1 cell population." (PMID 29946150, 2018). "In breast cancer, high PRMT5 expression, together with high PDCD4 (programmed cell death 4) levels predict overall poor survival." (PMID 29946150, 2018). "Ajuba functions as an obligate co-repressor for Snail and is essential for Snail-mediated breast cancer cell migration by recruiting PRMT5 to modulate histone modifications." (PMID 29299158, 2017). "To investigate the impact of PRMT5 depletion on tumor biology, we performed histological analysis of excised tumors in collaboration with a breast cancer pathologist and scored for pathological features currently used in patient diagnosis." (PMID 29262329, 2017). "Targeting of PRMT5 through depletion or inhibition reduces stem cell frequency in vitro and in vivo, implicating PRMT5 as important in breast cancer pathogenesis." (PMID 29262329, 2017). "In this study, we confirm that PRMT5 regulates the proliferation of bulk breast cancer cells and, more importantly, define a critical role for PRMT5 in the maintenance and propagation of BCSCs in vitro and in vivo through the epigenetic regulation of FOXP1." (PMID 29262329, 2017). "show that the arginine methyltransferase PRMT5 contributes to breast cancer stem cell function, in part through histone methylation regulating FOXP1 expression." (PMID 29262329, 2017). "Here, we focused on PRMT5, which has been reported to be upregulated in lung cancer, leukemia, lymphoma, ovarian cancer, and breast cancer." (PMID 26078354, 2015). "In breast cancer cells and xenograft breast cancer models, methylation of EGFR by PRMT5 promotes breast cancer cellular proliferation and tumour progression through activation of the ERK-mediated oncogenic pathway." (PMID 26420673, 2015). "This is exemplified by Programmed cell death 4 (PDCD4) protein in breast cancer, which shows increased tumorigenicity when over‐expressed with PRMT5 in an orthotopic model of breast cancer." (PMID 25475372, 2015). "Mutating KLF4 methylation sites suppresses breast tumour initiation and progression, and immunohistochemical stain shows increased levels of both KLF4 and PRMT5 in breast cancer tissues." (PMID 26420673, 2015). "In breast cancer patients whose tumors contain high level of PRMT5, elevated PDCD4 expression correlates with a worse outcome." (PMID 23202904, 2012).
breast carcinoma (continued). "For example, in breast cancer, PRMT5 upregulates FOXP1 expression via H3R2me2s." (PMID 41513606, 2026). "Given that SRSF1 has been linked to breast cancer and is methylated by PRMT5, we posited that SRSF1 may be one RBP that is methylated by PRMT5 contributing to splicing fidelity in BCSCs." (PMID 39695328, 2025). "Also, breast cancer cells treated with GSK591 showed decreased TCF3 exon 18A/18B ratio under hypoxia which indicated that PRMT5-mediated symmetric dimethylation is important for regulation of TCF3 alternative splicing event." (PMID 41150697, 2025). "A third trial will be evaluating the use of PRMT5 for breast cancer." (PMID 40869229, 2025). "This study suggests that PRMT5 inhibition could be a potential therapy in overcoming CDK4/6i resistance in advanced ER + breast cancer." (PMID 40650785, 2025). "Following doxorubicin treatment of breast cancer cells, PRMT5 induces nuclear translocation of the RNA demethylase ALKBH5, which removes m6A methylation from BRCA1 mRNA, stabilizing the transcript and enhancing DNA repair capacity to ultimately attenuate doxorubicin efficacy." (PMID 40919714, 2025). "To explore the mechanism by which PRMT5 regulates splicing in BCSCs, we focused on the RNA-binding protein SRSF1 because of its association with breast cancer, its ability to regulate cisplatin sensitivity, and that PRMT5-dependent methylation regulates splicing in AML cells." (PMID 39695328, 2025). "Therefore, we intended to study PRMT5-mediated acquisition of invasive potential of breast cancer cells under hypoxia." (PMID 41150697, 2025). "Together, these results indicated that PRMT5 is upregulated in breast cancer cells under hypoxia." (PMID 41150697, 2025). "However, hypoxia-mediated regulation of PRMT5 expression and its downstream effect on tumor progression in breast cancer models remain significantly less explored." (PMID 41150697, 2025). "PRMT5 inhibition increases the expression of DNA damage protein in breast cancer cell lines." (PMID 39201539, 2024). "Furthermore, in breast cancer cells, PRMT5 methylates KLF5 and inhibits its phosphorylation, ubiquitylation, and degradation." (PMID 38791992, 2024). "When PRMT5 is silenced in mammary epithelial cells, RORα protein is degraded and downregulated, and it consequently promotes mammary epithelial cells into transforming and initiating breast cancer." (PMID 38791992, 2024). "Additionally, we demonstrate the association between the PRMT5-FUS-Pol II axis and intron retention within genes that are enriched for cell cycle progression in ER+/RB-deficient breast cancer cells." (PMID 38480701, 2024). "However, it is reported that PRMT5 protein expression remains comparable among normal mammary epithelial cells, luminal breast cancer cells, and aggressive triple-negative breast cancer cells (TNBCs)." (PMID 38791992, 2024). "Thus, PRMT5 represents an actionable therapeutic vulnerability in breast cancers of this genotype and potentially fulfills an unmet need for patients with acquired resistance to CDK4/6i." (PMID 38480701, 2024). "In breast cancer, several investigations have shown that PRMT5 is elevated in its expression level in breast cancer cells and is correlated with a poor survival ratio in breast cancer patients, and it promotes cell invasion and proliferation and inhibits cell apoptosis in breast cancer cells." (PMID 38791992, 2024). "Interestingly, in contrast to the miR-204-5p expression pattern, PRMT5 was overexpressed in breast cancer." (PMID 37924099, 2023). "Furthermore, treatment with exosomes derived from breast cancer cells with circRHOT1 knockdown attenuated tumor growth in tumor-bearing nude mice, which was accompanied by a reduction in PRMT5 expression and an enhancement of miR-204-5p expression." (PMID 37924099, 2023).